LGALS9 (galectin 9)
Diseases named in the same sentence as LGALS9 in open-access papers (continued):
Sharing a sentence is not in itself a finding about the gene and the disease.
food allergy (7 papers, 2013 to 2025). Gastrointestinal disturbances, skin eruptions, or shock due to allergic reactions to allergens in food. "The involvement of IEC-derived and/or systemic galectin-9 as an immunomodulatory factor has also been substantiated in dietary intervention studies done in food allergy prevention models as well as in human infants." (PMID 33805597, 2021). "Galectin-9 is present in intestinal epithelial cells in low amount; however, the levels increase in patients with food allergy." (PMID 29950926, 2018). "Blocking galectin-9 in a mouse food allergy model inhibited the allergenic hypersensitivity status and Th2 polarization." (PMID 29950926, 2018). "Galectin-9 expression in intestine epithelial cells is upregulated in the intestine in patients with food allergy." (PMID 29950926, 2018). "However, previous studies have shown the predictive value of the IEC/PBMC model in vivo in a murine model for food allergy, by identifying dietary interventions with immunomodulatory properties in which galectin-9 had a key role." (PMID 35327576, 2022). "Despite its restrictions, the HT-29 transwell co-culture model was previously shown to have predictive value as the intervention with NDO not only identified an immunomodulatory role for galectin-9 in this in vitro model, but this was confirmed in murine models for food allergy." (PMID 32438601, 2020). "Furthermore, the results obtained from the IEC/PBMC model used were validated using in vivo animal models for food allergy, and in clinical samples of a NDO dietary intervention study, serum galectin-9 levels were shown to be enhanced." (PMID 35327576, 2022).
liver cancer (7 papers, 2014 to 2022). An epithelial or non-epithelial malignant neoplasm that arises from the liver. "The findings of this study suggest that miR-22 and galectin-9 may be valuable as novel targets for the treatment of human liver cancer." (PMID 29316949, 2018).
lymphoma (7 papers, 2020 to 2025). A malignant (clonal) proliferation of B- lymphocytes or T- lymphocytes which involves the lymph nodes, bone marrow and/or extranodal sites. "This AI-assisted integrative review investigated the neutrophil–T-cell axis, particularly the role of Galectin-9 (Gal-9), across adult T-cell leukemia/lymphoma (ATL), Sézary syndrome (SS), coronavirus disease 2019 (COVID-19), and psoriasis." (PMID 41562814, 2025). "The expression of galectin-9 is far less extensive than that of galectin-1 and galectin-3 in lymphoma." (PMID 35677161, 2022). "Therefore, increased galectin-9 level might reflect immune-related adverse effects of lymphoma biotherapy." (PMID 35677161, 2022). "Galectin-9/Tim-3 co-blockade has been studied extensively in other tumors and may be developed as a new therapy against PD1/PD-L1-resistant lymphoma." (PMID 35677161, 2022).
prostate carcinoma (7 papers, 2019 to 2025). A carcinoma that arises from epithelial cells of the prostate gland. "Other cell types expressed moderate levels and prostate cancer cells expressed lower but detectable levels of at least one variant of galectin-9." (PMID 31354733, 2019). "Intriguingly, in line with our observations that galectin-9 levels in PC3 prostate cancer cells are low compared to other cancer cells, these cells were recently reported to be rapidly killed by TALL-104 cells used in our work." (PMID 31354733, 2019).
systemic sclerosis (7 papers, 2018 to 2025). A chronic disorder, possibly autoimmune, marked by excessive production of collagen which results in hardening and thickening of body tissues. "The aim of this study was to determine the role of galectin-9 in the pathogenesis of bleomycin-induced systemic sclerosis (SSc)." (PMID 31937306, 2020).
chordoma (6 papers, 2020 to 2024). Chordomas are rare malignant tumors arising from embryonic remnants of the notochord in axial skeleton. "Other studies have shown that chordomas that expressed galectin-9 were also associated with more locally aggressive behavior, which correlated with a lower functional status for the patients." (PMID 38881706, 2024). "In contrast, our analyses revealed that high stromal Galectin-9 or PD-L1 expression in chordoma was associated with less aggressive tumor features and accurately reflected better prognosis." (PMID 35145510, 2021). "Chordomas positive for Galectin-9 (Gal9), a molecule that interacts with TIM3+ T-cells to induce apoptosis, had greater local invasiveness and lower Karnofsky performance status scores." (PMID 34067530, 2021). "The expression of both galectin-9 and PD-L1 are pro-apoptotic for tumor invading lymphocytes and may allow for the chordoma to escape the patient's anti-tumor immune response." (PMID 38881706, 2024). "Taken together, these data imply that stromal Galectin-9 or PD-L1 may influence chordoma phenotype and prognosis by promoting microenvironmental immune activation, although their specific regulatory networks require further investigation." (PMID 35145510, 2021). "Apart from tumor infiltrating lymphocytes expressing PD-L1/PD-1 and chordoma cells producing galectin-9, many chordomas may not be strongly immunogenic." (PMID 38881706, 2024).
esophageal cancer (6 papers, 2019 to 2025). A primary or metastatic malignant neoplasm involving the esophagus. "The effect of exogenously added galectin-9 on different esophageal cancer cell lines has also been explored." (PMID 36497271, 2022). "Regarding the role of galectin-9 in esophageal cancer, Hou and coworkers analyzed the expression of galectin-9 and its binding partner Tim-3 in tumor tissues obtained from 45 ESCC patients during curative surgical resection." (PMID 36497271, 2022). "The data on galectin-9 are limited but suggest that this family member might serve as a prognostic marker and therapeutic protein in esophageal cancer." (PMID 36497271, 2022). "In a previous report, the expression of galectin-9 and TIM-3 was evaluated using immunohistochemistry in human esophageal cancer tissues." (PMID 37047155, 2023).
head and neck squamous cell carcinoma (6 papers, 2025 to 2026). A squamous cell carcinoma that arises from any of the following anatomic sites: lip and oral cavity, nasal cavity, paranasal sinuses, pharynx, larynx, and salivary glands. "CircE7 suppresses the function of T cells by decreasing the expression of galectin-9 in head and neck squamous cell carcinoma (HNSCC)." (PMID 40710359, 2025). "A previous study has promoted an immune evasion mechanism in head and neck squamous cell carcinoma that activated ACC1 reduces H3K27 acetylation, resulting in reduced galectin-9 expression." (PMID 41169354, 2025). "Conversely, in certain settings such as head and neck squamous cell carcinoma (HNSCC), high TIM-3 expression correlates with enhanced NK cell cytotoxicity, and this enhancement can be counteracted by Galectin-9-mediated inhibition." (PMID 41544143, 2026).
Hepatitis (6 papers, 2012 to 2021). Inflammation of the liver. "It had been reported that increased serum levels of galectin-9 were associated with liver inflammation in patients with CHB33 and chronic hepatitis C34." (PMID 29127350, 2017). "Galectin-9, associated with liver inflammation, contributes to the expansion of mTregs through galectin-9/Tim-3 interaction." (PMID 29127350, 2017). "Taken together, our results are consistent with the observation that the TIM-3/galectin-9 interaction plays a critical role in Con A–induced hepatitis." (PMID 23118999, 2012). "To evaluate the direct effect of galectin-9 on hepatitis induced by concanavalin A (Con A) administration in mice and to clarify the mechanisms involved, we administered galectin-9 into mice, and evaluated its therapeutic effect on Con A-induced hepatitis." (PMID 23118999, 2012). "The aims of this study were to investigate the effect of galectin-9 on Con A-induced hepatitis in mice and to clarify the mechanisms involved." (PMID 23118999, 2012). "The TIM-3/galectin-9 interaction can be a potential therapeutic target given that pretreatment with galectin-9 protected mice from Con A–induced hepatitis." (PMID 23118999, 2012). "This is further supported by the observation that hepatitis became more severe if signals from endogenous galectin-9 were blocked with anti-TIM-3 mAb." (PMID 23118999, 2012). "In line with recent findings in HCV, we observed significantly elevated levels of galectin-9 in the circulation of those patients with HBV-related liver inflammation and also noted strong staining in Kupffer cells." (PMID 23112829, 2012). "Galectin-9 was detectable at increased concentrations in the sera of patients with active CHB-related liver inflammation (p = 0.02) and was strongly expressed by Kupffer cells within the liver sinusoidal network." (PMID 23112829, 2012). "As a prelude to exploring the value of manipulating TIM-3/galectin-9 interaction to influence the outcome of Con A-induced hepatitis, mice were injected with Con A and the expression pattern of TIM-3 on CD4+ T cells was measured at various times in the spleen." (PMID 23118999, 2012). "For this reason, we investigated whether galectin-9 administration protects mice from Con A-induced hepatitis." (PMID 23118999, 2012). "Thus, it is possible that galectin-9 plays a role in the pathology of Con A–induced hepatitis by regulating effector Th1 cells." (PMID 23118999, 2012). "Our findings constitute the first preclinical data indicating that interfering with TIM-3/galectin-9 signaling in vivo could ameliorate Con A-induced hepatitis." (PMID 23118999, 2012). "In the model of Con A-induced hepatitis, since inflammation appeared to be mainly orchestrated by IFN-γ producing CD4+ T cells, we investigated the effects of galectin-9 on the induction of apoptosis of CD4+ T cells." (PMID 23118999, 2012). "Compared with no treatment, galectin-9 pretreatment significantly reduced serum ALT and AST levels and improved liver histopathology, suggesting an ameliorated hepatitis." (PMID 23118999, 2012).
myelodysplastic syndrome (6 papers, 2017 to 2025). A clonal hematopoietic disorder characterized by dysplasia and ineffective hematopoiesis in one or more of the hematopoietic cell lines. "However, it remains unclear whether the Tim-3–galectin-9 pathway is associated with the pathophysiology of myelodysplastic syndromes (MDS)." (PMID 29179486, 2017). "Research has revealed that MDSCs from patients with myelodysplastic syndromes (MDS) exhibit high levels of galectin-9 (Gal-9)." (PMID 40303336, 2025).
breast tumors (5 papers, 2019 to 2025). "Consistently, hypomethylation of the LGALS9 promoter was found in primary breast tumor samples compared with controls, indicative of epigenetic upregulation." (PMID 40869319, 2025). "Here we report that primary breast tumors express significantly higher levels of Tim-3, and especially galectin-9, compared to healthy tissues of the same patients." (PMID 31354733, 2019). "Human breast tumor cells were also found to express galectin-9, where it was shown to be involved in cell aggregation, thus preventing metastasis." (PMID 31354733, 2019). "The level of galectin-9 mRNA in primary human breast tumor tissues was much higher compared to the normal tissue and, importantly, the ratio of galectin-9 mRNA in tumor and normal tissues was similar to the respective levels of protein detected." (PMID 31354733, 2019). "This is a strong indication that galectin-9 is capable of protecting breast tumor cells against cytotoxic cell-dependent killing." (PMID 31354733, 2019). "Analysis of blood plasma samples obtained from patients with both primary and metastatic breast tumors showed that levels of galectin-9 and soluble Tim-3 were lower compared to healthy donors." (PMID 31354733, 2019). "We found that studied breast tumors expressed significantly higher levels of both galectin-9 and Tim-3 compared to healthy breast tissues of the same patients and that these proteins were co-localized." (PMID 31354733, 2019). "We found that primary breast tumors expressed galectin-9, Tim-3, LPHN2, and FLRT3; as well as detectable amounts of LPHN3." (PMID 31354733, 2019). "In order to investigate the hypothesis of self-sustaining upregulation of TGF-β and galectin-9 expression in human cancer and embryonic cells we tested primary human breast tumours, primary AML cells as well as primary embryonic cells." (PMID 33295886, 2020). "Importantly, as in AML cells, Tim-3, and galectin-9 are co-localized in breast tumor cells and are capable to form complex." (PMID 31354733, 2019).
cerebral malaria (5 papers, 2019 to 2023). A sequestration of Plasmodium falciparum in the brain, which can cause coma and/or seizures. "Blockade of CD146 counter receptor using AA498 could block galectin-9-mediated cell adhesion and inflammation and disease pathogenesis in cerebral malaria." (PMID 36873388, 2023).
leptospirosis (5 papers, 2016 to 2023). A contagious bacterial infection caused by spirochetes of the genus Leptospira. "Using urine and blood samples of 112 patients with leptospirosis, osteopontin (OPN), galectin-9 (Gal-9) and other kidney-related biomarkers were measured to understand the pathological and diagnostic roles of OPN and Gal-9 in leptospirosis." (PMID 32610429, 2020).
liver fibrosis (5 papers, 2020 to 2025). "Galectin-9 is highly expressed in the liver and circulation in patients with chronic liver diseases, and higher serum galectin-9 levels are related to liver fibrosis progression." (PMID 31937306, 2020).
metastatic melanoma (5 papers, 2018 to 2024). A melanoma that has spread from its primary site to another anatomic site. "We decided to validate the increase in galectin-9, since it is elevated in plasma of patients with metastatic melanoma and correlates with poor survival." (PMID 38195762, 2024). "Indeed, considering that the serum level of galectin-9 was increased by an average of 3.6-fold in patients with metastatic melanoma, galectin-9 was proposed as a potential target for anticancer therapy." (PMID 32731422, 2020).
osteosarcoma (5 papers, 2021 to 2024). A usually aggressive malignant bone-forming mesenchymal neoplasm, predominantly affecting adolescents and young adults. "In this study, we characterized the expression of PD-1, PD-L1, TIM-3, Galectin 9, LAG-3, MHC Class II on diagnostic tissue samples from patients with Ewing sarcoma and osteosarcoma." (PMID 35938052, 2021). "In this study, we characterized the expression of PD-1, LAG-3, Tim-3, and their respective ligands PD-L1, major histocompatibility complex class II (MHC class II), Galectin-9 in children with Ewing sarcoma and osteosarcoma at diagnosis." (PMID 35938052, 2021). "We demonstrate high expression of TIM-3 and Galectin 9 positivity on immunohistochemistry staining in Ewing sarcoma, along with a relative lack of checkpoint receptor and ligand expression in osteosarcoma samples." (PMID 35938052, 2021). "Second, osteosarcoma tumor cells at diagnosis did not express any checkpoint receptors and ligands except Galectin-9, and non-tumor cells were also negative for PD-1, PD-L1, and LAG-3, suggesting that these tumors may be resistant to currently available checkpoint inhibitors if used at diagnosis." (PMID 35938052, 2021). "This expression pattern is different from osteosarcoma staining as none of the samples had positive PD-1 staining of tumor cells, and only 5 of 8 (62.5%) osteosarcoma samples stained positively for both TIM-3 and Galectin-9 in non-tumor cells." (PMID 35938052, 2021).
skin cancer (5 papers, 2014 to 2025). "Furthermore, we found that cell lines from brain, colorectal, kidney, blood/mast cell, liver, prostate, lung, and skin cancers expressed detectable amounts of both Tim-3 and galectin-9 proteins." (PMID 31354733, 2019).
squamous cell carcinoma (5 papers, 2014 to 2023). A carcinoma arising from squamous epithelial cells. "The overexpression of galectin-9, which is known to suppress the adhesion of tumor cells to the extracellular matrix and vascular endothelium, could be advantageous for the treatment of squamous cell carcinomas because it limits the formation of metastases." (PMID 24859692, 2014).
acute kidney injury (4 papers, 2021 to 2025). Sudden and sustained deterioration of the kidney function characterized by decreased glomerular filtration rate, increased serum creatinine or oliguria. "Research also reveals that galectin-9 plays a crucial role in protecting against acute kidney injury." (PMID 40904455, 2025). "In LPS-induced and ischemia-reperfusion (IR) induced acute kidney injury models, galectin-9 levels surged in plasma and kidney." (PMID 40904455, 2025).
airway hyperresponsiveness (4 papers, 2017 to 2024). "In a study using a murine model of allergic asthma it was shown that mammalian galectin-9 can modulate CD44-dependent leukocyte recognition of the extracellular matrix leading to a reduction in airway hyperresponsiveness." (PMID 36032131, 2022). "In another mucosal surface, the airways, administered galectin-9 inhibited airway hyperresponsiveness and by binding to CD44 and inhibited hyaluronan attachment; galectin-9 inhibited Th2-associated inflammation in the airways." (PMID 29950926, 2018).
autoimmune hepatitis (4 papers, 2021 to 2024). Hepatitis caused by autoantibodies. "Serum galectin-9 level was significantly higher in the patients with autoimmune hepatitis compared to the healthy volunteers (MD = 8.80, 95% CI = 7.61–9.99, p < 0.001)." (PMID 34778306, 2021).
brain tumor (4 papers, 2020 to 2025). "To this end, we determined the numbers of myeloid cells and lymphocytes in GL-261 WT and GL-261 LGALS9−/− primary brain tumor-bearing mouse CSF." (PMID 33093453, 2020). "Our analyses link galectin-9 expression with the survival of patients with CLL, kidney or brain tumors." (PMID 40775219, 2025).
co-infection (4 papers, 2019 to 2024). "TV-HPV co-infections HPV in contrast showed lower levels of galectin-9 (p <0.05), IL-1β and IL-8 (p <0.001)." (PMID 34422675, 2021). "Galectin-9, IL-1β and chemokines were up in TV-HIV and down in TV-HPV co-infections." (PMID 34422675, 2021). "Immunological responses were also consistent in that pro-inflammatory genes were induced in lice only and co-infected fish, whereas the anti-viral response, Mx, MH class I β, Galectin 9 and TRIM 16, 25 genes were down-regulated by lice infection prior to and shortly after co-infection with ISAv." (PMID 30650077, 2019).
cutaneous T cell lymphoma (4 papers, 2021 to 2025). "According to earlier studies, they found a link between the level of galectin-9 in patients’ serum and the severity of their cutaneous T-cell lymphoma." (PMID 37946029, 2024). "Human recombinant galectin-9 proteins have demonstrated robust anti-cancer activities in different models, such as in cutaneous T cell lymphoma (CTCL) and in a model of chronic myelogenous leukemia." (PMID 34944985, 2021).
endotoxemia (4 papers, 2022 to 2025). "Collectively, our results suggest that rhamnose signals via the CEACAM1/LGALS9-p38 axis, which suppresses endotoxemia-associated inflammation, and that rhamnose is a candidate anti-inflammatory agent for the control of infection-induced organ damage." (PMID 40708539, 2025).
eosinophilia (4 papers, 2010 to 2025). "Recent report showed that eosinophilia is related with the increased synthesis of galectin-9 (GAL-9) and osteopontin (OPN)." (PMID 20699002, 2010). "We studied novel pro-inflammatory molecules such as galectin-9 (GAL-9) and osteopontin (OPN) in a patient with insulin allergy because the involvement of these molecules in eosinophilia has been recently proposed." (PMID 20699002, 2010).